FRAS1 (Fraser extracellular matrix complex subunit 1)
Description:
Involved in extracellular matrix organization (By similarity). Required for the regulation of epidermal-basement membrane adhesion responsible for proper organogenesis during embryonic development (By similarity). Involved in brain organization and function (By similarity).
Synonyms: KIAA1500; FLJ22031; FLJ14927; FRASRS1
Tractability: Antibody: UniProt places it where antibodies can reach, with medium confidence; UniProt predicts a signal peptide or a membrane-spanning region; its Gene Ontology location is reachable by antibodies, with medium confidence. PROTAC: ubiquitination databases record sites on it.
Gene: Protein-coding gene on chromosome 4 (78,057,323 to 78,544,269, forward strand). Ensembl gene ENSG00000138759.
Subcellular location: Cell membrane
Gene Ontology:
Molecular function: protein binding; extracellular matrix structural constituent
Biological process: cell-matrix adhesion; epithelial structure maintenance; animal organ development; cell communication; system development
Cellular component: non-collagenous component of basement membrane; basement membrane; extracellular matrix; plasma membrane; membrane
Genetic constraint (gnomAD): Loss-of-function variants: 251 observed, 382.42 expected, observed/expected ratio (o/e) 0.66, 90% interval 0.59 to 0.73. The upper end of that interval is the gene's LOEUF score, 0.73, which puts it in group 2 of 6, group 1 being the genes least tolerant of losing a copy. Missense variants: 4,594 observed, 4,870.2 expected, observed/expected ratio (o/e) 0.94, 90% interval 0.92 to 0.97. Synonymous variants: 1,706 observed, 1,824.1 expected, observed/expected ratio (o/e) 0.94, 90% interval 0.9 to 0.97.
Gene-disease validity (ClinGen):
ClinGen rates the evidence that FRAS1 causes each of these diseases.
Fraser syndrome (autosomal recessive): Definitive. Fraser syndrome is a rare clinical entity including as main characteristics cryptophthalmos and syndactyly.
Homologues: Orthologues: chimpanzee FRAS1 (99% identical), macaque FRAS1 (96% identical), dog FRAS1 (89% identical), pig FRAS1 (88% identical), rabbit FRAS1 (86% identical), mouse Fras1 (85% identical), rat Fras1 (85% identical), guinea pig FRAS1 (82% identical). Paralogues in human: FREM2 (25% identical), FREM3 (15% identical), FREM1 (14% identical), ADGRV1 (10% identical), SLC8A1 (4% identical), SLC8A3 (4% identical), SLC8A2 (4% identical).
Diseases named in the same sentence as FRAS1 in open-access papers:
FRAS1 is named in the same sentence as 53 diseases in open-access papers, as found by Europe PMC text mining. Sharing a sentence is not in itself a finding about the gene and the disease. The quoted sentences say what the papers report.
Fraser syndrome (31 papers, 2010 to 2025). "Regarding the PPI network, FREM2 interacts with several proteins known to be associated with Fraser syndrome, such as FRAS1, FREM1, and GRIP1." (PMID 41426592, 2025). "A mutation in the FRAS1 gene serves as the fundamental trigger for Fraser syndrome, leading to prenatal mortality in human fetuses." (PMID 38396565, 2024). "FRAS1 mutations can lead to an autosomal recessive malformation syndrome known as Fraser syndrome (FS), characterized by occlusion, syndactyly, and reproductive system defects." (PMID 38396565, 2024). "Biallelic variants in FREM2, FREM1, or FRAS1 result in Fraser syndrome (MIM 607830; 608945; 604597), a rare autosomal recessive malformation syndrome characterized by cryptophthalmos, syndactyly, urogenital abnormalities, and dental anomalies." (PMID 37046432, 2023). "Fraser syndrome in humans results if any of the core members of the Fraser complex (Fras1, Frem1, Frem2) are mutated." (PMID 37047755, 2023). "Mutations in FRAS1 are known to be associated with Fraser syndrome, a disorder characterized by multisystem abnormalities, including malformations in the craniofacial, urogenital, and respiratory systems." (PMID 37626805, 2023). "FRAS1 mutations have been confirmed to cause an extremely rare autosomal recessive genetic disorder named Fraser Syndrome (FRASRS), and seem to be responsible for non-syndromic unilateral renal agenesis." (PMID 35646073, 2022). "Numbers of mutations or large deletions of FRAS1 lead to the dermal-epidermal detachment, which are responsible for Fraser syndrome with cryptophthalmos characterized by eyelid anomalies." (PMID 35456484, 2022). "For example, Fraser syndrome commonly features kidney agenesis and is caused by mutations of Fraser extracellular matrix complex subunit 1 (FRAS1) or related genes such as FREM2." (PMID 35575937, 2022). "Patients with Fraser syndrome, a genetic disorder that presents with congenital malformations such as cryptophthalmos, syndactylism and reno‐urinary anomalies, is caused by FRAS1 mutations." (PMID 33131207, 2021). "Rarely, CHAOS is part of underlying Fraser syndrome, which has other characteristic anomalies (cryptophthalmos-syndactyly) and can be confirmed by mutation analysis of FRAS1." (PMID 25190454, 2015). "Existing Fras1 mutant mice harbour null alleles and the bfb mutant mouse is therefore the first missense model of Fraser syndrome." (PMID 24143185, 2013). "The bfb mouse is the first ENU-induced Fras1 allele and the first missense mutation in a mouse model of Fras1-mediated Fraser syndrome." (PMID 24143185, 2013). "Mutation of FRAS1 in humans causes Fraser Syndrome which involves a series of related phenotypes to the blebs mutants." (PMID 23469164, 2013). "The growth in our understanding of both Fraser syndrome and mutant mice phenocopying Fraser syndrome features have been intimately linked and mutation in the FRAS1 gene in human and mouse models of Fraser syndrome was simultaneously reported in both species." (PMID 24143185, 2013). "Fraser syndrome cases are attributable to mutations in either FRAS1 (Fraser syndrome 1) or FREM2 (FRAS1-related extracellular matrix protein 2), with these genes accounting for approximately 40% of cases." (PMID 22690109, 2012). "Autozygosity mapping and candidate sequencing revealed that many Fraser syndrome cases are due to mutations in the genes encoding the proteins FRAS1 or FREM2, which belong to a family of large extracellular matrix proteins." (PMID 20419147, 2010).
Fraser syndrome (continued). "Two of the disease genes underlying Fraser Syndrome in humans were identified as FRAS1 or FREM2, which encode structurally related basement membrane proteins." (PMID 20419147, 2010). "Fras1 has become known for its mutations, resulting in sub-epidermal blistering and the fusion of eyelids and digits, as well as the malformation of lungs and kidneys, also known as Fraser syndrome in humans." (PMID 38396565, 2024). "Mutations of the FRAS1 gene appear to cause Fraser syndrome." (PMID 36982551, 2023). "However, in one large literature review, abnormal lung lobulation was documented in 5/117 (4.3%) of cases of Fraser syndrome, which can be caused by recessive mutations in FRAS1, FREM2 and GRIP1." (PMID 23536828, 2013). "Mutations in FRAS1 or FREM2 were found in approximately 50% of investigated cases of Fraser Syndrome, whereas the molecular lesions underlying the other half remain unknown." (PMID 20419147, 2010). "These include FRAS1, FREM1, and GRIP1, which are known to be associated with Fraser syndrome, suggesting a coordinated role in the biological processes underlying this disorder." (PMID 41426592, 2025). "In humans and mice, recessive loss-of-function mutations in FRAS1 and GRIP1 cause the rare, clinically overlapping congenital disorders Fraser Syndrome and Ablepharon Macrostomia Syndrome." (PMID 26110643, 2015). "Here we noted the compound heterozygous missense mutations c.1918C>T (p.640R>C) and c.5205C>A (p.1735H>Q) in FRAS1 (MIM 607830, ENST00000264895), in which mutations are associated with Fraser syndrome (MIM 219000)." (PMID 24476948, 2014). "For example, mutations in the zebrafish orthologues of human FRAS1, FREM1 and FREM2 recapitulate the epidermal blistering of distal appendages seen in Fraser Syndrome." (PMID 24400120, 2014). "Lack of FRAS1 causes Fraser syndrome, a multisystem malformation that can include craniofacial, urogenital, and respiratory system abnormalities." (PMID 30124164, 2018). "Inherited mutations in FRAS1, and FREM2, have been associated with development of Fraser syndrome." (PMID 27047539, 2016). "Similar multi-organ defects have been reported in humans with GRIP1 mutations consistent with Fraser syndrome, a syndrome found with deletion of specific GRIP1 interacting proteins including Frem1 (Fras1 related extracellular matrix 1) and Fras1 (Fraser syndrome 1)." (PMID 27631377, 2016). "Recessive mutations in FRAS1, FREM2, and GRIP1 cause Fraser syndrome which is characterized by cognitive impairments, cryptophthalmos, syndactyly, genital and renal anomalies and a range of other structural defects including CDH, lung lobulation defects and anal anomalies (OMIM #219000)." (PMID 23536828, 2013). "The phenotypes of Fraser syndrome caused by variants in FREM2, FREM1, or FRAS1 are not distinguishable." (PMID 37046432, 2023).
renal agenesis (7 papers, 2013 to 2022). Renal agenesis (RA) is a form of renal tract malformation characterized by the complete absence of development of one or both kidneys (unilateral RA or bilateral RA respectively), accompanied by absent ureter(s). "This is further supported by a recent publication identifying biallelic FRAS1 variants in four cases of bilateral renal agenesis." (PMID 35990004, 2022). "Other interesting candidate adaptive genes include HLA-DMA involved in immunity, FRAS1 associated with renal agenesis, SREBF2 related to female reproduction and DISC1 associated with response to the ultraviolet (UV) exposure." (PMID 34691999, 2019). "The FRAS1-related extracellular matrix 1 transcript, with which the Ma2AP5 sequence aligns with 95% identity, is associated with craniofacial and renal embryonic formation and development, and its mutation leads precisely to renal agenesis in mice." (PMID 36428413, 2022). "However, one patient in this pooled exome study with a compound heterozygous mutation in FRAS1 had a sibling with previous intrauterine demise secondary to bilateral renal agenesis, suggesting various FRAS1 mutations may cause more severe renal phenotypes." (PMID 35990004, 2022). "In FRAS1-deficient mice, lack of ureteric bud initiation from the mesonephric duct, or failure of the ureteric bud to penetrate the metanephric mesenchyme, causes the metanephric mesenchyme to undergo fulminant apoptosis, resulting in renal agenesis." (PMID 23536828, 2013). "Apoptosis of cells in the metanephric mesenchyme, leading to renal agenesis, is also seen in mice that lack the cytosolic adapter protein GRIP1, which plays a critical role in trafficking FRAS1 and FREM2 to the plasma membrane." (PMID 23536828, 2013). "Human mutations of Fraser syndrome 1 (FRAS1), encoding a matrix molecule coating the outer surface of developing kidney tubules, causes bilateral renal agenesis (i.e. both kidneys and ureters are absent)." (PMID 26315301, 2016). "Given the known interactions between these proteins, it is not surprising that FREM1-, FRAS1-, FREM2- and GRIP1-deficient mice have overlapping patterns of defects that include cryptophthalmos and syndactyly–which are likely to be secondary effects of blister formation–and renal agenesis." (PMID 23536828, 2013).
lung cancer (5 papers, 2016 to 2024). A malignant neoplasm involving the lung. "It is the first study about the correlation between m6A modification of FRAS1 and lung cancer cell proliferation." (PMID 36008805, 2022). "This was the first to identify the role of FRAS1 on the promotion of cell proliferation in lung cancer." (PMID 36008805, 2022). "FRAS1 is involed in cell adhesion and it was previously reported that FRAS1 knockdown reduces A549 lung cancer cell migration and invasion through downregulation of focal adhesion signaling." (PMID 29435133, 2018). "FRAS1 has also been implicated in ERK signaling and influence migration and invasion of lung cancer cell line by influencing FAK signaling, suggesting its role in tumorigenesis and metastasis of lung cancer." (PMID 27047539, 2016). "We wondered whether there was m6A modification of FRAS1 mRNA in lung cancer." (PMID 36008805, 2022). "For lung cancer cell lines (A549), FRAS1 knockdown reduced cell migration and invasion but not cell proliferation." (PMID 38473784, 2024). "FRAS1 knockdown by shRNA could significantly reduce the migration and invasion ability of A549 cells through down‐regulation of FAK signaling in non‐small cell lung cancer." (PMID 33131207, 2021).
gastric cancer (4 papers, 2020 to 2022). A primary or metastatic malignant neoplasm involving the stomach. "FRAS1 was reported to facilitate the liver metastasis of gastric cancer through activating the EGFR and PI3K signaling pathways." (PMID 36008805, 2022). "Similar to gastric cancer, our data demonstrated that the FRAS1 levels were significantly elevated in primary tumors and liver metastatic nodes of CRC patients." (PMID 33131207, 2021). "In particular, knockout of FRAS1 inhibits proliferation of gastric cancer cells through caspase activity increment and cell cycle arrest both in vitro and in vivo." (PMID 34439271, 2021). "Recent studies show that FRAS1 contributes to the malignant phenotype of NSCLC, gastric cancer, colorectal cancer." (PMID 36008805, 2022).
breast carcinoma (3 papers, 2013 to 2022). "In addition, FRAS1 was more frequently mutated in metastatic breast cancer than in primary breast cancer." (PMID 35874676, 2022).
metastatic tumors (3 papers, 2022). "Another study demonstrated that FRAS1 mutation may be associated with an increase in the development of metastatic disease or death from prostate cancer." (PMID 35874676, 2022). "Among these, FRAS1, PTPRC, MACF1 and MYH8 mutations have been found to be more enriched in other metastatic tumors." (PMID 36033490, 2022).
congenital diaphragmatic hernia (2 papers, 2013 to 2023). A posterolateral defect of the diaphragm that allows passage of abdominal viscera into the thorax, leading to respiratory insufficiency and persistent pulmonary hypertension with high mortality. "Similarly, recessive mutations in Frem1 have been shown to cause congenital diaphragmatic hernia (CDH) which has not been documented in mice with Fras1, Frem2 or Grip1 mutations." (PMID 23536828, 2013).
epilepsy (2 papers, 2018 to 2023). A brain disorder characterized by episodes of abnormally increased neuronal discharge resulting in transient episodes of sensory or motor neurological dysfunction, or psychic dysfunction.
hypospadias (2 papers, 2022). Hypospadias is the displacement of the urethral meatus on the ventrum of the penis. "Besides the BRAF variant, we also identified a co-segregating variant in FRAS1, a gene known to be associated with hypospadias." (PMID 35606856, 2022).
chronic kidney disease (1 paper, 2023). Impairment of the renal function secondary to chronic kidney damage persisting for three or more months. "Fraser extracellular matrix complex subunit 1 (FRAS1) genetic variant was significantly associated with the progression of chronic kidney disease to end-stage renal disease." (PMID 37974210, 2023).
congenital adrenal hyperplasia (1 paper, 2022). Congenital adrenal hyperplasia (CAH) is an inherited endocrine disorder caused by a steroidogenic enzyme deficiency that is characterized by adrenal insufficiency and variable degrees of hyper or hypo androgyny manifestations, depending of the type and the severity of the disease. "Upregulation of genes associated with other diseases, renal dysfunction or cancer was also observed, such as Fras1 (Fraser syndrome 1), Cyp21a1 (congenital adrenal hyperplasia), Dbh (associated with kidney dysfunction), and Akr1c1/Myt1/Myf6/Scg2 (kidney cancer)." (PMID 36130284, 2022).
DiGeorge syndromes (1 paper, 2016). "These syndromes mainly include Townes–Brocks (SALL1), CHARGE (CHD7), Fraser (FRAS1), and DiGeorge syndromes (del22q11)." (PMID 28003020, 2016).
Frasier syndrome (1 paper, 2014). Frasier syndrome is characterized by the association of male pseudohermaphrodism and glomerular nephropathy. "Fras1 is a gene mutated in Frasier Syndrome and encodes a basement membrane-associated protein important in renal development." (PMID 25127402, 2014).
hepatocellular carcinoma (1 paper, 2022). A malignant tumor that arises from hepatocytes. "TERT, CSMD1, FRAS1 and ND5 are mutated in 28.6%, 5.7%, 5.2% and 5.3% of human hepatocellular carcinomas." (PMID 35557512, 2022). "These genes include the telomerase reverse transcriptase gene, TERT, CSMD1, a putative tumor suppressor that is frequently mutated in human hepatocellular carcinoma associated with HBV infection, FRAS1 and the mitochondrial encoded gene ND5." (PMID 35557512, 2022).
Hyperkeratosis (1 paper, 2021). Hyperkeratosis is a histopathological term defining a thickened stratum corneum and may be present in many different skin conditions, with many possible overlaps. "The overlapping DEGs included genes associated with hyperkeratosis (upregulated LCE3E and TMEM45A), wound healing (upregulated KRT17, IL36G, TNC, and TGFBI), barrier defects (downregulated FRAS1 and BCL11A), and response to infection (upregulated IL36G, ADAP2, DFNA5, RFTN1, LITAF, and TMEM173)." (PMID 34506598, 2021).
lymph node metastasis (1 paper, 2021). "Univariate analysis for OS showed that lymph node metastasis, circ102049 expression and FRAS1 were all prognostic factors for poor prognosis." (PMID 33131207, 2021).
metastatic prostate carcinoma (1 paper, 2024). A carcinoma that arises from the prostate gland and has spread to other anatomic sites. "A polymorphism in the promoter of FRAS1 is a candidate SNP associated with metastatic prostate cancer, and FRAS1 mRNA was highly expressed in tissues rich in muscle cells or fibers in this study." (PMID 38396565, 2024).
non-small cell lung carcinoma (1 paper, 2022). A group of at least three distinct histological types of lung cancer, including non-small cell squamous cell carcinoma, adenocarcinoma, and large cell carcinoma. "In this study, we assessed the role of m6A methyltransferase METTL3 in FRAS1-involved cell proliferation and colony formation of non-small cell lung cancer (NSCLC) cell lines." (PMID 36008805, 2022).
Renal cyst (1 paper, 2020). A fluid filled sac in the kidney. "A patient with right renal agenesis and left renal cysts carried compound heterozygous mutations in FRAS1 (p.Tyr2273* from the father and p.Gly3456Asp from the mother)." (PMID 32164334, 2020).
type 2 diabetes mellitus (1 paper, 2022). A type of diabetes mellitus that is characterized by insulin resistance or desensitization and increased blood glucose levels. "The top-ranking pathways enriched in the shared genes include “ECM-receptor interaction” (FRAS1/SPP1, P value = 4.92e-03), “growth hormone synthesis, secretion and action” (ADCY5/SOCS3, P value = 8.84e-03) and “type II diabetes mellitus” (SOCS3, P value = 0.055)." (PMID 35606885, 2022).